IGF1 (insulin like growth factor 1)
Diseases named in the same sentence as IGF1 in open-access papers (continued):
Sharing a sentence is not in itself a finding about the gene and the disease.
tumor (continued). "IGF-1 was detected in lung lavage fluid and macrophage conditioned media, and was significantly elevated in tumor-bearing lungs and tumor-educated macrophage-conditioned media." (PMID 21699731, 2011). "Regarding the mode of action, IGF-1 pathway plays a role in insulin-related tumor promotion in the colon." (PMID 22174655, 2011). "OS cells have been shown to be IGF1-dependent for growth, and inhibiting growth hormone release in mice decreased IGF1 serum levels and inhibited tumor growth." (PMID 21619704, 2011). "Tumor-educated BAL macrophages produced significantly more IGF-1 than naïve macrophages, both basally and in response to IL-4 stimulation." (PMID 21699731, 2011). "Tumor-educated macrophages produce more IGF-1 on a per-cell basis than naïve BAL macrophages, consistent with the elevated levels of TH2-like cytokines reported in the lung tumor microenvironment." (PMID 21699731, 2011). "BALF from tumor-bearing lungs contained 3.5-times more IGF-1 than BALF from naïve mice, while EGF levels were unchanged." (PMID 21699731, 2011). "Several approaches to target IGF–1 signaling resulted in the inhibition of the growth of a broad range of tumor cells." (PMID 22514573, 2011). "Measurement of IGF-1 levels in MØCM from primary naïve and tumor-educated BAL macrophages showed that tumor-educated macrophages produced significantly more IGF-1 than naïve macrophages (grey bars)." (PMID 21699731, 2011). "Angiogenesis, the formation of new blood vessels, has a vital function in tumour growth and spread, and IGF-1 and insulin induce angiogenesis in vitro and in vivo." (PMID 21081932, 2011). "A dose of 50 ng/ml IGF-1 stimulated neoplastic growth to a similar extent as MØCM; 2 ng/mL IGF is the reported EC50 for IGF-1 stimulated proliferation in vitro as well as the concentration detected in the BALF of tumor-bearing mice in vivo." (PMID 21699731, 2011). "The pathogenesis of tumor cachexia is still not fully understood but a multifactorial process including pro-inflammatory cytokines like IL-6 or TNF-α, neuroendocrine hormones, downregulation of IGF-1 and tumor proteolysis inducing factor is assumed." (PMID 21892933, 2011). "IGF-1 stimulated neoplastic proliferation and mediated a significant portion of macrophage-induced tumor cell growth in culture." (PMID 21699731, 2011). "We found that rapamycin suppresses IGF-1 stimulated F-actin reorganization and migration in various tumor cell lines by inhibiting mTORC1-mediated 4E-BP1 and S6K1 pathways." (PMID 20485667, 2010). "Together these data demonstrate that IGF-1 overexpression contributes to both initiation and promotion of skin tumorigenesis." (PMID 21297902, 2010). "The IGF type 1 receptor (IGF-IR) pathway, initiated by the ligands IGF-1 and IGF-2, is associated with cellular mitogenesis, angiogenesis, tumour cell survival, and tumourigenesis in various tumour cell lines." (PMID 20628389, 2010). "For example, IGF-1 signalling is essential for tumourigenesis, maintenance of tumour growth, and ESFT cell migration." (PMID 20606682, 2010). "One potential concern for the use of growth factors such as IGF-1 for clinical applications is the effect as a tumor promoter." (PMID 20698985, 2010). "Using of the two-stage protocol with DMBA plus various tumor promoters, the K1.IGF-1 transgenic mice develop more tumors/mouse more rapidly than their non-transgenic littermates." (PMID 21297902, 2010). "Our previous studies have shown that rapamycin suppresses IGF-1 stimulated motility in various tumor cell lines in part by inhibiting mTORC1-mediated 4E-BP1 and S6K1 pathways." (PMID 20485667, 2010). "Pinkston-Gosse and Kenyon have identified 29 daf-16/FOXO-regulated genes that act in the insulin/IGF-1 pathway to influence C. elegans tumor growth." (PMID 21084729, 2010).
tumor (continued). "These animals did not displaypronounced muscle hypertrophy but had increased levels of circulating IGF-1,mild cardiac hypertrophy, an increased incidence of late onset neoplasia(unpublished observation)." (PMID 20157530, 2009). "Another widespread effect of CR was increased expression of phosphatase and tensin homolog (Pten), which is a tumor suppressor that inhibits IGF-1 signals by preventing activation of the PI3K/Akt signaling pathway." (PMID 19968875, 2009). "Within the tumour environment, it is likely that the secretion of IGFBP4 in the presence of the IGFBP4 protease (produced by host cells, such as fibroblasts and osteoblasts) provides a steady supply of IGF1 to the tumour to support its growth and angiogenesis." (PMID 19536088, 2009). "A-928605 is an optimized pyrazolopyrimidine that has previously been reported to have an IGF1R in vitro enzymatic IC50 of 37 nM as well as an IC50 value of 90 nM for inhibition of cellular IGF1R phosphorylation induced by IGF1 in A431 tumor cells." (PMID 19732452, 2009). "The in vitro data suggested that IGFBP4 would inhibit IGF1-stimulated growth of 4T1.2 tumours by blocking its effects on tumour cell and endothelial cell proliferation and VEGF production." (PMID 19536088, 2009). "Despite a poorly differentiated tumor frequency of 66% at 30 weeks of age, serum IGF-1 concentrations gradually declined after 30 weeks of age." (PMID 19171036, 2009). "Insulin-like growth factor-1 is a potent stimulator of cellular proliferation and survival as well as tumour growth." (PMID 18182993, 2008). "It is well established that bioactivity of free insulin growth factor 1 (IGF-1) increases tumor turnover rate." (PMID 17953765, 2007). "The median values of relative expression of IGF-1 mRNA were 0.469 (0.281–0.711) 0.762 (0.338–0.874) in tumour and ANCT respectively (p = 0.0002)." (PMID 16725048, 2006). "In the future, we can study the potential in vivo effects of IGF-1 inhibition on tumour growth and angiogenesis in MM." (PMID 14997210, 2004). "The slope of this regression line was also significant and showed that CT-2A tumour growth decreased as IGF-1 levels decreased (0.20±0.02; t=2.43; Y=−6.84+0.20X)." (PMID 14520474, 2003). "Body weights, tumour weights, plasma glucose, β-hydroxybutyrate (β-OHB), and insulin-like growth factor 1 (IGF-1) were measured 13 days after tumour implantation." (PMID 14520474, 2003). "Tumor presence was associated with increased expression of LH and FSH receptors and c-KIT, while angiogenic and proliferative factors (PCNA, Ki-67, IGF-1, VEGF, and ERα) showed lower expression." (PMID 42121783, 2026). "Patients with tumor-related AGHD had a lower 5-year mean IGF-1 SDS." (PMID 40076636, 2025). "Additionally, tumor stroma is responsible for further secretion of IGF-1, worsening tumor aggressiveness." (PMID 40299428, 2025). "In tumor tissue, the IGF-1/IGF-1R interaction may be increased, activating intracellular PI3K/AKT and MAPK signaling pathways, increasing proliferation, and causing local depletion of IGF-1." (PMID 41303367, 2025). "Thus, monocytes and macrophages, which can make up to 50% of the tumor mass and are mostly activated as M2-like macrophages, can secrete many of the cytokines associated with EMT, including TGFβ, TNFα and IGF1." (PMID 41462963, 2025). "Intermittent fasting 147 may inhibit tumor growth by triggering autophagy and diminishing the levels of growth factors such as insulin-like growth factor-1 (IGF-1)." (PMID 39744225, 2025). "Tumor-related neovascularization, on the other hand, may also induce cell proliferation in a paracrine fashion, e.g., through insulin-like growth factor-1 (IGF-1) and platelet-derived growth factor (PDGF) produced by endothelial cells." (PMID 40362659, 2025). "The decrease of IGF-1 was verified on protein level by staining tumor sections." (PMID 41429766, 2025).
tumor (continued). "Although IGF1 signaling and iCAF phenotypes have been linked to therapy resistance in other tumor types, our study did not directly evaluate drug response." (PMID 41463024, 2025). "The binding of IGF-1 to IGF-1R triggers PI3K pathway upregulation in tumor cells." (PMID 40427130, 2025). "However, central tumor of men with high serum IGF-1 contained more PD-L1 positive cells than tumors of men with low serum IGF-1." (PMID 41184420, 2025). "Moreover, lower IGF-1 levels lead to reduced angiogenesis and inflammation, two processes that support tumor progression." (PMID 39940361, 2025). "Notably, we also observed an inverse correlation between tumor PR expression and serum IGF-1 concentration." (PMID 41262902, 2025). "Due to the suppression of the negative feedback loop of IGF-1 on the pituitary gland, pegvisomant has a modest risk of increasing tumour size." (PMID 40672042, 2025). "In fact, feeding a reduced protein diet to mice suppresses tumor growth, an effect mediated through both cancer cell intrinsic mechanisms (e.g. reducing insulin-like growth factor 1 signaling and inhibiting mTOR activity), as well as enhancing the anti-tumor immune response." (PMID 40105196, 2025). "IGF1 can promote tumor cell invasion and metastasis by modulating cell adhesion and angiogenesis." (PMID 41333209, 2025). "Research has demonstrated that IGF-1 may facilitate tumor development by stimulating cellular proliferation and inhibiting the process of apoptosis." (PMID 41210510, 2025). "Long-acting formulations of octreotide can normalize IGF-1 and GH levels, and shrink tumor volume." (PMID 41221256, 2025). "Moreover, hyperinsulinemia and elevated IGF-1 bioavailability in T2DM create a systemic environment that favors tumor initiation and progression via enhanced activation of mitogenic pathways." (PMID 41157306, 2025). "However, the IGF1 neutralization antibody reversed this effect, reducing tumor formation from 100% to 58.8% (7/12)." (PMID 40659611, 2025). "Younger age, higher preoperative GH and/or IGF-1 levels, group 2b clinicopathological classification, Knosp grade IV, MRI, T2-weighted tumor hyperintensity and sparsely granulated cytokeratin expression patterns are also related to worse postoperative outcomes." (PMID 40276548, 2025). "There are several mechanisms by which GH and IGF-1 may promote cell differentiation that result in neoplasms." (PMID 40088375, 2025). "Furthermore, the IGF1 neutralization antibody significantly reduced tumor number in both the antibody-alone group (10 per mouse) and the GSK-J4 combination group (3.5 per mouse)." (PMID 40659611, 2025). "Age, sex, preoperative GH and IGF-1 levels, maximal tumor diameter, Hardy’s and Knosp’s classifications, MRI T2-weighted tumor intensity, and cytokeratin expression pattern, as well as the experience of the neurosurgeon, are frequently related to postoperative outcomes." (PMID 40276548, 2025). "This suggests IGF1 may create a favorable microenvironment for tumor development by inhibiting apoptosis and promoting growth, a mechanism also observed in other malignancies." (PMID 41333209, 2025). "When analyzing only for the subgroup of patients with gigantism only three publications reported IGF1 with a mean of 1328.3 (μg/L) and IGF1 index of 3.0, seven publications reported GH with a mean of 17.8 (μg/L), and three publications reported tumor size with a mean of 8 mm, range 4–12 mm." (PMID 40941625, 2025). "The IGF1/IGF1R system dysregulation is involved in the proliferation of numerous tumours as well as the IGF1/IGF1R system inhibition by statins, which may be of preventive and/or therapeutic value in some tumours such as prostate." (PMID 40874517, 2025). "This implies that HFD-driven tumor growth depends not only on IGF-1 signaling but on FAO pathways." (PMID 40521210, 2025).
tumor (continued). "This may be worth comparing against CSF-1 receptor inhibition, which prevents the polarizing effect of this cytokine on TAMs but results in upregulation of insulin-like growth factor-1 (IGF-1) signaling that promotes tumor relapse." (PMID 40844085, 2025). "Its insulin-lowering action may indirectly limit tumor growth given the role of insulin and IGF-1 in PC development and progression." (PMID 40940951, 2025). "Gut-SCFAs, while generally anti-inflammatory in healthy states, may under certain dysbiotic conditions promote tumor growth via IGF-1 pathway activation or influence androgen metabolism." (PMID 41384118, 2025). "Moreover, IGF1 signaling is established to upregulate oncogene expression and enhance tumor cell proliferation in vitro." (PMID 40359201, 2025). "Importantly, neutralisation of secreted IGF1 or genetic ablation of IGF1R in tumor cells abrogated these effects, substantiating an essential paracrine loop." (PMID 41275311, 2025). "IGF-1 promotes cell growth and inhibits apoptosis, processes that contribute to tumor formation." (PMID 40493660, 2025). "In this context, serum IGF-1 could serve as a hormone-related biomarker, while circulating tumor DNA (ctDNA) may provide a complementary, tumor-specific readout for treatment response and residual disease." (PMID 41262902, 2025). "Specifically, combining oncolytic herpes simplex virus-1 (oHSV) and RTx, two modalities that converge on IGF1-Rmediated resistance, may enhance therapeutic efficacy and overcome tumor-intrinsic resistance." (PMID 41510300, 2025). "Increased insulin/IGF-1 signalling may promote tumour growth directly through insulin receptors or regulation of IGF and their binding proteins (IGFBP), which are involved in cell survival and proliferation." (PMID 39941741, 2025). "Additionally, studies have shown that IGF-1 overexpression can enhance MYC expression, and MYC also can promote tumor cell growth through paracrine signaling mediated by the IGF-1/IGF-1R axis." (PMID 40160318, 2025). "In addition, PAPP-A enhances IGF-1 signaling, which indirectly suppresses tumor antigen presentation and facilitates immune evasion in ES." (PMID 40978053, 2025). "By lowering IGF-1 and insulin, IF modulates the inflammatory tumour microenvironment." (PMID 41335382, 2025). "Finally, the development of the nomogram, integrating CTP score, IGF-1, and tumour volume, demonstrates substantial predictive power with an AUC of 0.84 for 2-year survival, suggesting a reliable tool for clinical decision-making." (PMID 39624154, 2025). "However, the consumption of complex carbohydrates is encouraged, as they have a lower glycemic index and regulate the activity of insulin-like factor binding protein 3 (IGFPB-3), which blocks the action of IGF-1, thus lowering tumor growth signaling." (PMID 40046187, 2024). "Different molecular mechanisms connect the GH/IGF1 axis to tumor progression." (PMID 38892104, 2024). "GH receptor antagonists (pegvisomant) inhibit IGF-1 production and are less commonly used as antisecretory drugs for GH-secreting PitNETs, because they may stimulate tumor growth." (PMID 39224564, 2024). "Nevertheless, the knockdown of FOXC1 significantly mitigated these effects of IGF-1 on tumor cells." (PMID 38413558, 2024). "In vivo models reveal that stromal cells, not tumor cells, are major sources of IGFs, with non-immune stromal cells and tumor-associated macrophages (TAMs) expressing Igf1 and Igf2 mRNA." (PMID 39273251, 2024). "Insulin-like growth factor-1 (IGF-1), essential for cellular proliferation, when inhibited, leads to significant shifts, including increased cellular accumulation at the G2M/S phase, augmented apoptosis, and reduced invasive capabilities of tumor cells." (PMID 38988712, 2024).
tumor (continued). "Interestingly, Western blot analysis showed increased IGF-1 protein levels in OVCAR3 compared to non-tumor cells, confirming the overexpression previously observed at the mRNA level." (PMID 39596005, 2024). "It mediated anti‐carcinogenic activity through restrictions on the proliferation of cells and tumor cell growth via upregulating estrogen receptor beta (ER‐β) and downregulating of 1R insulin‐like growth factor 1 (IGF‐1) in MCF‐7 and T‐47D cell in a dose‐dependent way." (PMID 38230908, 2024). "However, it has been shown in a murine model that drugs targeting IGF1R (Insulin-like Growth Factor-1) improve lifespan with a reduction of neoplasm only in females, which aligns with our findings." (PMID 39107837, 2024). "In general, GH levels are more of a tumor marker and IGF-1 levels are a marker of disease activity." (PMID 39803157, 2024). "Therefore, appropriate doses of GHRAs that result in IGF1 lowering can be expected to significantly attenuate the tumor-promoting effects mediated by IGF1R activation." (PMID 39000545, 2024). "Additionally, CR decreases poor prognosis markers such as IGF1, pAKT, and PI3K and induces changes in the gut microbiome linked to anti-tumor effects." (PMID 39195514, 2024). "However, a non-matrix binding and protease-resistant recombinant IGFBP-2 suppress tumor growth and angiogenesis in a mouse model through IGF-1 depended actions." (PMID 39273251, 2024). "This suggests that IGF1 signaling molecules could potentially attract immune cells within the tumor microenvironment." (PMID 38189813, 2024). "Therefore, our results preferentially reflect the effects of blocking IGF1-independent and autocrine/paracrine actions of GH in the tumor milieu." (PMID 39000545, 2024). "GH is an anterior pituitary hormone with postnatal whole-body endocrine actions that regulates longitudinal growth, organ development, metabolic homeostasis, and hepatic production of >70% of circulating insulin-like growth factor 1 (IGF1), another well-studied tumor-promoting factor." (PMID 39000545, 2024). "When this allele was combined with a null allele for a tumor suppressor gene causing germline tumors, a complete absence of tumor development was observed, suggesting that the lack of IGF1 effectively conferred resistance to tumors." (PMID 38255007, 2024). "Additionally, Plasmodium-derived hemozoin that accumulated in tumor-associated macrophages inhibited IGF-1 signaling through the PI3-K and MAPK signaling pathways and thereby decreased the expression of MMP-9 in tumor-associated macrophages." (PMID 39367471, 2024). "We hypothesized that consuming a low GI diet would inhibit tumor growth by decreasing the activation of the insulin/IGF-1 signaling axis compared to a high GI diet." (PMID 38082056, 2024). "Likewise, treatment of nude mice bearing human gastric tumor (NCI-N87) with MR-356, significantly inhibited the growth of the tumor and, lowered serum IGF-1 levels." (PMID 39592529, 2024). "The lower level of IGF-1 in the elderly may increase the dedifferentiation of tumor cells in TC, which may explain why 95% of TCs are well differentiated in children and adolescents." (PMID 39104813, 2024). "Osteoclasts and tumor cells contribute to bone destruction, and neurotrophins, cytokines (IL-1β and TNFα), and other factors (ATP, TGFβ1, IGF-1, and sclerostin) play roles, suggesting potential intervention targets for improved pain management and enhanced patient quality of life." (PMID 38474093, 2024). "IGF-1 promotes the formation of new blood vessels, supplying the tumor with the essential nutrients and oxygen needed for growth and metastasis, by upregulating angiogenic factors like vascular endothelial growth factor (VEGF), through the activation of MAPK and PI3K/ AKT cascades." (PMID 39273251, 2024).